IGFBP6 (insulin like growth factor binding protein 6)
Diseases named in the same sentence as IGFBP6 in open-access papers (continued):
Sharing a sentence is not in itself a finding about the gene and the disease.
hepatocellular carcinoma (4 papers, 2011 to 2026). A malignant tumor that arises from hepatocytes. "This information may be used for developing new therapies by regulating IGFBP-6 assembly with IGF-II to minimize the risk of viral associated hepatocellular carcinoma." (PMID 21548981, 2011). "The cells in hepatoma and various phosphorylated forms can secret IGFBP-6." (PMID 34032605, 2021). "We can conclude that during HCV/HBV infection, O-β-GlcNAc of IGFBP-6 at Ser 204 diminish their binding with IGF-II, increase IGF-II cellular expression and promote cancer progression which can lead to hepatocellular carcinoma." (PMID 21548981, 2011). "Similarly, studies have also reported the tumor-promoting role of IGF2BP1, IGF2BP3, IGFBP6 and IGFL2 in several cancers such as hepatocellular carcinoma, pancreatic and prostate cancers." (PMID 34061869, 2021).
lung carcinoma (4 papers, 2012 to 2023). "Gain of cyclin E or loss of IGFBP6 in lung cancer cells significantly increased Smo inhibitor response." (PMID 22923130, 2012). "IGFBP-6 plays several complex roles as a mediator of airway inflammation, participating in the pathogenesis of asthma, fibrosis, as well as lung cancer." (PMID 36902237, 2023). "Starting from this data, in the next paragraph, we will discuss IGFBP-6’s role in lung cancer pathogenesis and progression." (PMID 36902237, 2023). "While high IGFBP6 levels were present in some lung tumors, it is notable that lung cancers with both high cyclin E and reduced IGFBP6 expression significantly (P<0.0001) increased Gli1 expression." (PMID 22923130, 2012). "These transgenic lung cancers are also shown to express low levels of IGFBP6 and GILZ versus the adjacent normal lung." (PMID 22923130, 2012). "Two shRNAs were selected to reduce IGFBP6 expression independently in ED-1 lung cancer cells derived from a transgenic mouse that expressed wild-type cyclin E." (PMID 22923130, 2012). "Moreover, the Smoothened (Smo) inhibitors of the Hedgehog (HH) pathway are activated in lung cancers and IGFBP-6 is differentially expressed in human normal-malignant lung tissue arrays." (PMID 36902237, 2023). "Nevertheless, the mechanisms underlying the effects of MIP-1γ, SDF-1α and IGFBP-6 in lung cancer have not been clearly defined." (PMID 37929799, 2023). "IGFBP-6, an IGFBP family member that can increase the half-life of circulatory insulin-like growth factors (IGFs), is a serum biomarker associated with poor prognosis in lung cancer and immune cell regulation." (PMID 37929799, 2023). "In this review, we assess the current state of IGFBP-6’s multiple roles in respiratory diseases, focusing on its function in the inflammation and fibrosis in respiratory tissues, together with its role in controlling different types of lung cancer." (PMID 36902237, 2023). "In a study based on lung cancer cell lines, transgenic and transplantable murine lung cancer models, and a human normal-malignant lung tissue array, the sensitivity to the Smo inhibitor cyclopamine correlated with low IGFBP-6." (PMID 36902237, 2023). "Among them, IGFBP2, IGFBP3, IGFBP4, IGFBP6 and IGFBP7 showed higher expression levels, especially in gastric, liver and lung cancer cell lines; conversely, IGFBP1, IGFBP5 and IGFBPL1 showed relatively lower expression, particularly in colorectal, gastric and kidney cancer cell lines." (PMID 37088808, 2023).
neuroblastoma (4 papers, 2005 to 2022). Neuroblastoma (NB) is the most common solid, extracranial childhood tumor. "More specifically, neuroblastoma cells undergo a decrease in both cell proliferation and tumorigenic potency as a result of exogenous IGFBP-6 expression as IGFBP-6 sequesters IGF-2 preventing a mitogenic response in tumor cells." (PMID 29387091, 2017). "Notably, IGFBP6 has antitumor effects in many types of cancer, including neuroblastoma, colon, ovarian, and prostate cancer." (PMID 35832140, 2022). "Notably, IGFBP6 inhibits proliferation and tumor development in many cancer types, including neuroblastoma, colon, ovarian, prostate, and rhabdomyosarcoma." (PMID 30231881, 2018). "This phenomenon has been observed in many types of cancer, including neuroblastoma, colon, and ovarian; however, the endogenous source of IGFBP6 was not previously known." (PMID 30231881, 2018).
prostate carcinoma (4 papers, 2005 to 2022). A carcinoma that arises from epithelial cells of the prostate gland. "Drivdahl reported that the upregulation of IGFBP-6 occurs in association with the activity of 1,25-dihydroxyvitamin D3 in prostate cancer cells, and suggested a role for IGFBP-6 in the suppression of prostate tumour cell growth." (PMID 15846301, 2005). "This prompted us to investigate the effect of IGFBP-6 on androgen-independent prostate cancer PC-3 cells." (PMID 15846301, 2005). "From the immunohistochemical analysis of IGFBP-6 using biopsy samples from androgen-independent prostate cancer, we found IGFBP-6 expression in androgen independent prostate cancer, and that DES treatment increased the IGFBP-6 staining intensity of the cancer cells in one sample." (PMID 15846301, 2005). "We next studied the effect of recombinant IGFBP-6 on prostate cancer cells." (PMID 15846301, 2005). "However, IGFBP-6 is upregulated at the mRNA and protein level in androgen-independent human prostate cancer PC-3 cells." (PMID 15846301, 2005).
steatosis (4 papers, 2022 to 2026). Increased lipid within the cytoplasm of cells. "IGFBP6 is significantly positively associated with steatosis and has been identified as a contributor to hepatic inflammation and fibrosis." (PMID 41208894, 2025). "Specifically, IGFBP-6 levels are higher in relation to increasing steatosis, while the hepatic expression of IGFBP-6 is strongly positively associated with fibrosis, steatosis grade, and NAFLD activity score." (PMID 35457175, 2022). "IGFBP-6 is significantly positively associated with steatosis, and it was recently reported as a potential contributor of hepatic inflammation and fibrosis." (PMID 35457175, 2022). "Analyses of these proteins showed a negative correlation between IGFBP2, IGFBP4, and steatosis grade (r = −0.49, p < 0.02; r = −0.12, p < 0.02), while IGFBP6 and IGFBP7 were positively associated with steatosis (r = 0.25, p < 0.005; r = 0.35, p < 0.0001)." (PMID 36831184, 2023). "Because both transcriptional control and post-translational modification influence IGFBP-6 abundance and binding properties, compartment-aware, stimulus-resolved assays are needed to interpret circulating and tissue IGFBP-6 during steatosis, fibrosis, and viral hepatitis." (PMID 41511360, 2026).
chronic kidney disease (3 papers, 2019 to 2022). Impairment of the renal function secondary to chronic kidney damage persisting for three or more months. "The levels of IGFBP6 are particularly high in children with chronic renal failure, and correlate inversely with the glomerular filtration rate." (PMID 30608957, 2019). "IGFBPs not only enhance the effects of IGFs, but also have IGF-independent activities; for instance, IGFBP1 and IGFBP6 levels increase in chronic renal failure." (PMID 30608957, 2019). "Since cell senescence and apoptosis are also important in development and chronic kidney disease, we speculated that IGFBP-6 might be involved in development and fibrosis by regulating apoptosis of renal cells, but more basic research evidence is needed." (PMID 35002740, 2021).
diabetes (3 papers, 2021 to 2023). "After adjusting for age, duration of diabetes, sex, hypertension, and dyslipidemia, higher levels of sTNFRI (odds ratio [OR] = 2.18, 1.1 × 10−3), sTNFRII (OR = 1.52, 1 × 10−2), and IGFBP6 (OR = 3.62, 1.8 × 10−3) were significantly associated with CAD." (PMID 37822049, 2023). "IGFBP-3, IGFBP-4, IGFBP-5, IGFBP-6 are involved in different kidney disease such as diabetes, FSGS and CKD physiological process as apoptosis proteins, IGFBP-7 has been used in clinical practice as a biomarker for early diagnosis and prognosis of AKI." (PMID 35002740, 2021). "IGFBP6 and PDK4 were upregulated in patients with diabetes and diabetes-related complications." (PMID 36276976, 2022).
Hepatic fibrosis (3 papers, 2022 to 2025). The presence of excessive fibrous connective tissue in the liver. "The post-interventional dynamics of physiologically relevant adipokines and hepatokines (ANGPTL4, CCL5, GDF15, GPNMB, IGFBP6), as well as their correlation with fat mass reduction and improvement of liver fibrosis, were analyzed." (PMID 36430499, 2022). "In hepatic fibrosis, IGFBP-6 has emerged as a key marker; reduced IGFBP-6 expression is seen in chronic hepatitis C as it progresses to fibrosis, and in NAFLD patients with fibrosis, elevated hepatic IGFBP-6 levels strongly correlate with advanced fibrosis." (PMID 41226289, 2025). "This strongly predictive character for hepatic fibrosis was exclusively observed for GDF15 but not for ANGPTL4, CCL5, GPNMB, and IGFBP6." (PMID 36430499, 2022).
Insulin resistance (3 papers, 2017 to 2021). Increased resistance towards insulin, that is, diminished effectiveness of insulin in reducing blood glucose levels. "IGFBPs are known regulators of insulin resistance, with increased serum IGFBP6 levels identified within type 1 diabetes, and thus high systemic glucose." (PMID 31028944, 2019).
leiomyoma (3 papers, 2008 to 2022). A well-circumscribed benign smooth muscle neoplasm characterized by the presence of spindle cells with cigar-shaped nuclei, interlacing fascicles, and a whorled pattern. "The importance of controlling uterine IGF bioactivity has been demonstrated in the human uterus where low levels of IGFBP-6 and higher levels of IGF-II are associated with uterine leiomyomas (fibroids), compared with normal endometrium." (PMID 18258405, 2008). "DUSP1, IGFBP6 and NEDD9 were down-regulated in the majority of leiomyomas compare to matched normal tissues in accordance with microarray data." (PMID 25268745, 2014).
pancreatic cancer (3 papers, 2009 to 2025). "In this study, we demonstrated that Gli1 protein bound to the promoters of IGFBP6 and Bcl-2 by XChIP-PCR assays, which suggested that Gli1 facilitates transcriptions of IGFBP6 and Bcl-2 in a parallel manner in pancreatic cancer cells." (PMID 19736394, 2009). "In conclusion, Gli1 directly facilitates expressions of IGFBP6 and Bcl-2 at the same time in cultured pancreatic cancer cells." (PMID 19736394, 2009). "Moreover, many studies have demonstrated the downregulation of IGFBP6 expression in cancer; in contrast, several studies have shown upregulation of IGFBP6 in pancreatic cancer and adrenocortical cancer." (PMID 35832140, 2022). "Moreover, upregulation of IGFBP6 and Bcl-2 following the reactivation of Shh-Gli1 pathway in pancreatic cancer tissues suggest regulation model of Shh-Gli1 pathway to IGFBP6 and Bcl-2 is similar in vivo." (PMID 19736394, 2009). "We studied the relationship of Shh-Gli1 signaling pathway with proliferation and apoptosis of pancreatic cancer cells and the regulation of transcription factor Gli1 to insulin-like growth factor binding protein 6 (IGFBP6) and Bcl-2 genes at the level of transcription." (PMID 19736394, 2009). "Finally PCNA, IGFBP6 and Bcl-2 mRNA were upregulated as well as Shh or Gli1 in pancreatic cancer tissues (p < 0.01)." (PMID 19736394, 2009). "Since IGFBP6 and Bcl-2 genes have been proved to be target genes of transcription factor Gli1, we hypothesize that Shh-Gli1 pathway are associated with IGF pathway and Bcl-2 family in pancreatic cancer." (PMID 19736394, 2009). "Our study reveals that Gli1 maintained cell survival by binding the promoter regions and facilitating transcription of IGFBP6 and Bcl-2 genes in a parallel manner in pancreatic cancer cells and suggests it may be one of the mechanisms of Shh-Gli1 signaling pathway in pancreatic cancer." (PMID 19736394, 2009). "QRT-PCR was performed to evaluate the levels Shh, Gli1, IGFBP6, IGF2, PCNA, Bcl-2, Bax and Bak1 mRNA in pancreatic cancer tissues (n = 6) and corresponding cancer side tissues (n = 6)." (PMID 19736394, 2009). "The results showed that GAPDH, Bcl-2 and IGFBP6 were amplified from the positive contrasting template, which confirmed the presence of GAPDH, Bcl-2 and IGFBP6 genes in the total chromatin fraction of pancreatic cancer cells." (PMID 19736394, 2009).
allergic asthma (2 papers, 2022). A asthma with a basis in a pathological type I hypersensitivity reaction. "IGFBP6 was found to be highly expressed in eosinophils, and it has also been reported that IGFBP6 is associated with allergic asthma and thymic atrophy." (PMID 35832140, 2022). "IGFBP-6 RNA is highly expressed in eosinophils and IGFBP-6 gene has been linked to allergic asthma the latter suggesting it may play a role in Th2 response, favoring an imbalance of the immune response towards immunosuppressive stimuli." (PMID 35457175, 2022).
dyslipidemia (2 papers, 2021 to 2023). "The Odds ratio (OR) remained unchanged for sTNFRI (1.72, p=0.00001), sTNFRII (1.45, p=0.0027), sIL2Rα (1.40, p=0.0023), IGFBP6 (1.51, p=0.0032) and CRP (1.47, p=0.0046) after adjusting for confounding variables, HbA1C, hypertension and dyslipidemia." (PMID 33868296, 2021).
gastric adenocarcinoma (2 papers, 2020 to 2023). "The low expression of IGFBP6 is related to poor clinical outcomes and unfavorable prognosis in gastric adenocarcinoma." (PMID 33282953, 2020). "In stomach adenocarcinoma, IGFBP1 is upregulated, but IGFBP2 and IGFBP6 are downregulated." (PMID 37088808, 2023).
liver cancer (2 papers, 2012 to 2026). An epithelial or non-epithelial malignant neoplasm that arises from the liver. "Profibrotic, inflammatory, hypoxia/redox, and metabolic cues (including PTMs like O-GlcNAc) dynamically tune IGFBP-6 abundance and function across disease states and liver cancers." (PMID 41511360, 2026).
melanoma (2 papers, 2015 to 2021). A malignant, usually aggressive tumor composed of atypical, neoplastic melanocytes. "In our study, we first found that up-regulation of IGFBP5 decreased HIF1α expression and the other IGFBPs family members, IGFBP2, IGFBP4, IGFBP6, and IGFBP7 to some extent in melanoma cells." (PMID 26010068, 2015).
Myocardial fibrosis (2 papers, 2025). "In cardiovascular disease, alterations in IGFBP-6 levels can affect myocardial fibrosis, vascular function, and inflammation." (PMID 41169887, 2025). "IGFBP6 may also aggravate myocardial fibrosis by regulating SENP2 maturation of myocardial fibroblasts, thereby regulating cholesterol flow." (PMID 41208894, 2025).
osteoarthritis (2 papers, 2016 to 2017). A noninflammatory degenerative joint disease occurring chiefly in older persons, characterized by degeneration of the articular cartilage, hypertrophy of bone at the margins and changes in the synovial membrane. "IGFBP6 was measured in RA patients and healthy donors (HD) sera by Luminex xMAP® technology and in ST of RA patients and osteoarthritis (OA) controls by immunofluorescence." (PMID 28572803, 2017).
Sepsis (2 papers, 2019 to 2025). Sepsis is defined as life-threatening organ dysfunction caused by a dysregulated host response to infection. "Our multicenter, cross-age cohort study identified insulin-like growth factor binding protein 6 (IGFBP6) as a critical regulator in sepsis diagnosis, prognosis, and mortality risk evaluation." (PMID 40892465, 2025). "CCL2 supplementation or IGFBP6 deficiency effectively counteracts these pathological effects, aligning with prior sepsis studies." (PMID 40892465, 2025). "As a biomarker of the disease, high levels of IGFBP6 indicate the risk of sepsis and dire predictions for survival." (PMID 40892465, 2025). "ROC curve analysis confirmed the superior diagnostic accuracy of IGFBP6 for pediatric sepsis, with the discovery and validation cohorts showing AUCs of 0.90 (95% CI, 0.85-0.96) and 0.96 (95% CI, 0.94–0.98), respectively." (PMID 40892465, 2025). "Collectively, IGFBP6 emerges as an endogenous driver of sepsis pathogenesis, positioning it as a dual diagnostic biomarker and therapeutic target." (PMID 40892465, 2025). "IGFBP6 is a diagnostic and prognostic biomarker for sepsis across age groups." (PMID 40892465, 2025). "Serum IGFBP6 levels were markedly elevated in pediatric patients with sepsis versus healthy controls, with hierarchical increases in septic shock and in the number of non-survivors." (PMID 40892465, 2025). "Genetic ablation of IGFBP6 conferred significant survival advantages in CLP-induced polymicrobial sepsis in a sex-independent manner." (PMID 40892465, 2025). "To characterize the relationship between IGFBP6 and the progression of sepsis, we constructed cross-age, multicenter sepsis cohorts." (PMID 40892465, 2025). "Our study establishes IGFBP6 as a therapeutic target in sepsis through 4 key findings: (a) Elevated circulating IGFBP6 levels in adult and pediatric patients with sepsis correlate with disease severity compared with healthy and non-septic infection controls." (PMID 40892465, 2025). "Consistent findings were observed in mouse lung epithelial (MLE-12) and intestinal epithelial (MODE-K) lines, suggesting epithelial cells and macrophages constitute primary sources of systemic IGFBP6 elevation during sepsis." (PMID 40892465, 2025). "Although accumulating evidence highlights the pivotal role of innate immune cells in sepsis progression, the mechanistic involvement of IGFBP6 in modulating these cells remains elusive." (PMID 40892465, 2025). "IGFBP6 orchestrates sepsis pathogenesis via PHB2-dependent immunosuppression and macrophage dysfunction, establishing it as a diagnostic-therapeutic nexus." (PMID 40892465, 2025). "Considering that IGFBP6 plays a role in exacerbating immune damage during the pathological process of sepsis, inhibiting IGFBP6 expression is expected to be a potential approach to alleviate symptoms." (PMID 40892465, 2025). "Although IGFBP6-mediated regulation of CCL2 is independent of IGF2, the potential involvement of IGF2-dependent pathways in IGFBP6’s modulation of sepsis progression remains an open question requiring systematic investigation." (PMID 40892465, 2025). "To delineate the pathophysiological implications of IGFBP6 elevation, we employed an IGFBP6 knockout (Igfbp6–/–) mouse in polymicrobial sepsis models." (PMID 40892465, 2025). "As primary effector cells for bacterial clearance in sepsis, macrophages are critically regulated by IGFBP6, which was previously shown to inhibit their chemotaxis." (PMID 40892465, 2025). "Our study identifies IGFBP6 as a critical regulator that simultaneously undermines both resistance and disease tolerance, thereby exacerbating sepsis severity." (PMID 40892465, 2025). "We have presented an extensive study focused upon IGFBP6 as a direct indicator of sepsis diagnosis and progression, which is also fortuitous as a mechanism for alleviation and survival." (PMID 40892465, 2025).